SF3B2 (splicing factor 3b subunit 2)
Description:
Component of the 17S U2 SnRNP complex of the spliceosome, a large ribonucleoprotein complex that removes introns from transcribed pre-mRNAs. The 17S U2 SnRNP complex (1) directly participates in early spliceosome assembly and (2) mediates recognition of the intron branch site during pre-mRNA splicing by promoting the selection of the pre-mRNA branch-site adenosine, the nucleophile for the first step of splicing. Within the 17S U2 SnRNP complex, SF3B2 is part of the SF3B subcomplex, which is required for 'A' complex assembly formed by the stable binding of U2 snRNP to the branchpoint sequence in pre-mRNA. Sequence independent binding of SF3A and SF3B subcomplexes upstream of the branch site is essential, it may anchor U2 snRNP to the pre-mRNA. May also be involved in the assembly of the 'E' complex. Also acts as a component of the minor spliceosome, which is involved in the splicing of U12-type introns in pre-mRNAs.
Synonyms: SF3b145; SAP145; SF3b1; Cus1; CFM; HFM; SF3b150
Tractability: Small molecule: a structure with a bound ligand is known. PROTAC: UniProt records ubiquitination sites on it; ubiquitination databases record sites on it; its protein half-life has been measured.
Target class: Other nuclear protein
Gene: Protein-coding gene on chromosome 11 (66,050,729 to 66,069,308, forward strand). Ensembl gene ENSG00000087365.
Subcellular location: Nucleus; Nucleus speckle
Subcellular location (Human Protein Atlas): Nuclear speckles
Pathways (Reactome):
Metabolism of RNA: mRNA Polyadenylation; mRNA Splicing - Major Pathway; mRNA Splicing - Minor Pathway
Chromatin organization: CHD1 and CHD2 subfamily
Disease: Dengue Virus-Host Interactions
Gene Ontology:
Molecular function: protein binding; RNA binding
Biological process: mRNA splicing, via spliceosome; mRNA processing; RNA splicing; spliceosomal snRNP assembly; spliceosome conformational change to release U4 (or U4atac) and U1 (or U11); U2-type prespliceosome assembly
Cellular component: catalytic step 2 spliceosome; nuclear speck; nucleus; precatalytic spliceosome; spliceosomal complex; U11/U12 snRNP; U12-type catalytic step 2 spliceosome; U12-type precatalytic spliceosome; U12-type spliceosomal complex; U2-type catalytic step 1 spliceosome; U2-type precatalytic spliceosome; U2-type spliceosomal complex; nucleoplasm; U2 snRNP
Genetic constraint (gnomAD): Loss-of-function variants: 19 observed, 110.57 expected, observed/expected ratio (o/e) 0.17, 90% interval 0.12 to 0.25. The upper end of that interval is the gene's LOEUF score, 0.25, which puts it in group 1 of 6, group 1 being the genes least tolerant of losing a copy. Missense variants: 715 observed, 1,137 expected, observed/expected ratio (o/e) 0.63, 90% interval 0.59 to 0.67. Synonymous variants: 391 observed, 416.03 expected, observed/expected ratio (o/e) 0.94, 90% interval 0.86 to 1.02.
Homologues: Orthologues: macaque SF3B2 (99% identical), chimpanzee SF3B2 (99% identical), dog SF3B2 (98% identical), pig SF3B2 (98% identical), rat Sf3b2 (96% identical), mouse Sf3b2 (96% identical), rabbit SF3B2 (95% identical), guinea pig SF3B2 (86% identical), zebrafish sf3b2 (65% identical), tropical clawed frog sf3b2 (64% identical), Caenorhabditis elegans sftb-2 (34% identical).
Diseases named in the same sentence as SF3B2 in open-access papers:
SF3B2 is named in the same sentence as 35 diseases in open-access papers, as found by Europe PMC text mining. Sharing a sentence is not in itself a finding about the gene and the disease. The quoted sentences say what the papers report.
craniofacial microsomia (6 papers, 2021 to 2025). "De novo or transmitted haploinsufficiency‐causing SF3B2 variants have been identified in 20 individuals from seven families with craniofacial microsomia (MIM:164210) with lateral oral cleft in some probands." (PMID 41427026, 2025). "In particular, Patient 42 presented a heterozygous stop-gain variant in the SF3B2 gene, whose pathogenic variants were reported in 2021 to be causative of craniofacial microsomia (MIM: # 164210)." (PMID 36979683, 2023). "Notably, one pathogenic variant linked to a de novo mutation is found in the SF3B2 gene, which is associated with craniofacial microsomia." (PMID 40136557, 2025). "Additionally, genes like PDE4DIP, UBXN11, and AXIN1 are associated with hepatocellular carcinoma, and a de novo mutation in the SF3B2 gene relates to craniofacial microsomia." (PMID 40136557, 2025). "For instance, splicing factor 3b subunit 2 (SF3B2) and splicing factor 3b subunit 4 (SF3B4) are associated with craniofacial microsomia (MIM:164210; SyCL/P), and Nager syndrome (MIM:154400; SyOFC), respectively." (PMID 41427026, 2025).
prostate carcinoma (5 papers, 2020 to 2025). A carcinoma that arises from epithelial cells of the prostate gland. "High SF3B2 expression promotes tumor progression in CRPC by increasing the expression of androgen receptor splicing variant 7 (AR-V7) in prostate cancer." (PMID 35715826, 2022). "High SF3B2 expression also causes minor changes in RNA splicing in genes other than AR-V7 in prostate cancer, suggesting other roles for SF3B2 in gene expression." (PMID 35715826, 2022). "High SF3B2 expression is associated with poor prognosis, at least in prostate cancer, bladder cancer, acute myeloid leukemia (AML), lung adenocarcinoma, breast cancer, and head and neck squamous cell carcinoma (HNSCC)." (PMID 35715826, 2022). "In agreement with our results, SF3B2 conferred an aggressive phenotype in prostate cancer and was associated with poor overall survival and progression-free survival in many cancers, such as bladder, lung, and breast cancers." (PMID 34611311, 2021). "Previous studies indicated that high SF3B2 expression was associated with aggressive phenotypes in prostate cancer." (PMID 34611311, 2021). "However, AR-V7 is specifically expressed in prostate cancer, whereas high SF3B2 expression is associated with a poor prognosis in patients with at least six types of cancer." (PMID 35715826, 2022). "In prostate cancer, SF3B2 directly binds to CE3 of AR and controls alternative splicing of AR to produce AR-V7." (PMID 32106418, 2020). "On the other hand, another component of SF3b complex SF3B2 is increased in CRPC and prostate cancers with high expression of AR-V7 and associates with poor progression-free survival in prostate cancer patients." (PMID 32106418, 2020). "Therefore, SF3B2, SF3B1 and the SF3b complex may be good candidates of therapeutic targets, and small chemicals inhibiting/modulating the SF3b complex might be promising for prostate cancer treatment." (PMID 32106418, 2020).
colon cancer (2 papers, 2018 to 2021). "It has been reported that miR-3189-3p inhibits the proliferation and migration of colon cancer cells by targeting SF3B2 and p63RhoGEF, respectively." (PMID 29342841, 2018). "SF3B2 protein expression was significantly increased in colon tumors compared to adjacent non-tumor tissues." (PMID 34611311, 2021).
hepatocellular carcinoma (2 papers, 2020 to 2025). A malignant tumor that arises from hepatocytes. "For instance, SF3b2 was reported to positively regulate human prostate cancer and has been implicated to be overexpressed in hepatocellular carcinoma (HCC)." (PMID 32140746, 2020).
Nager syndrome (2 papers, 2021 to 2025). Nager syndrome, also called Nager acrofacial dysostosis (NAFD) is a congenital malformation syndrome characterized by mandibulofacial dystosis (malar hypoplasia, micrognathia, external ear malformations) and variable preaxial limb defects. "Whereas external ear defects appear frequently in those with SF3B2 variants, they are restricted to the tragal region and ear canal, and the malar and mandibular hypoplasia that are hallmark features of Nager syndrome appear to be less severe in probands with SF3B2 variants." (PMID 34344887, 2021). "Whereas the majority of children with Nager syndrome require craniofacial surgery to maintain airway patency, none of the probands with SF3B2 haploinsufficiency in this cohort required a tracheostomy or early mandibular surgery for airway compromise." (PMID 34344887, 2021).
ear malformation (1 paper, 2021). "All four probands harboring these SF3B2 variants presented with ear malformations limited to the tragus, mandibular hypoplasia, preauricular and/or facial tags, and cervical ribs in the three with radiographs available for study." (PMID 34344887, 2021). "Individuals with SF3B2 variants showed phenotypic homogeneity via external ear malformations consistently involving the tragus, and mandibular hypoplasia." (PMID 34344887, 2021).
head and neck squamous cell carcinoma (1 paper, 2022). A squamous cell carcinoma that arises from any of the following anatomic sites: lip and oral cavity, nasal cavity, paranasal sinuses, pharynx, larynx, and salivary glands. "Our findings indicate that SF3B2 has a dual function in both transcription and RNA stability, leading to head and neck squamous cell carcinoma progression." (PMID 35715826, 2022). "High SF3B2 expression leads to poor prognosis in patients with head and neck squamous cell carcinoma and to progression of tumor growth in mice." (PMID 35715826, 2022).
liver cancer (1 paper, 2026). An epithelial or non-epithelial malignant neoplasm that arises from the liver. "Together, these findings establish lysine myristoylation as a reversible regulatory modification on a spliceosomal component and reveal HDAC11-catalyzed de-myristoylation of SF3B2 as a mechanism that can tune alternative splicing in liver cancer cells." (PMID 42124652, 2026).
lung carcinoma (1 paper, 2020). "Therefore, targeting RNF113A or SF3B2 is a strategy to circumvent the acquired resistance of lung cancer cells to Cisplatin." (PMID 32152280, 2020).
medulloblastoma (1 paper, 2021). A malignant, invasive embryonal neoplasm arising from the cerebellum. "SF3B2 has been reported as a potential gene marker in many diseases including medulloblastoma in DisGeNET and has appeared as one of the significantly dysregulated proteins in our discovery dataset." (PMID 34055594, 2021).
ovarian carcinoma (1 paper, 2023). A malignant neoplasm originating from the surface ovarian epithelium. "Studies have shown that SF3B1, SF3B2, and SF3B3 can regulate target gene expression by alternative splicing to promote cancer progression, also SF3B3 controls AS in renal cancer and SF3B4 in ovarian cancer by regulating AS of RAD52." (PMID 37091785, 2023).
squamous cell carcinoma (1 paper, 2019). A carcinoma arising from squamous epithelial cells. "Moreover, in samples from clinical squamous cell cancer, six genes (GAL, GSTP1, MRPL11, MRPL21, SF3B2, and YIF1A) at 11q13.1–13.3 and one gene (GALR1) at 18q23 showed significant differences in expression between normal and tumor samples." (PMID 31552180, 2019).
cancer (9 papers, 2016 to 2025). A tumor composed of atypical neoplastic, often pleomorphic cells that invade other tissues. "Cancerous mutations in splicing factor SF3B2 have been reported to affect the ubiquitinylation pathways and hence associated with cancer." (PMID 34055594, 2021). "High SF3B2 expression is also associated with poor overall survival in patients with other cancers." (PMID 35715826, 2022). "They found that urinary glyphosate level was associated with the methylation level of 24 CpG sites in the promoters of genes including some related to cancer, such as SF3B2, MSH4, and ERCC8." (PMID 39200696, 2024). "Along with SFRS4 (number 13 in the top list of “universal” reference genes), three genes that participate in pre-mRNA splicing and processing pathways (SF3A1, SF3B2, and SFRS3) are present in the top 10 of promising pan-cancer RGs." (PMID 30881377, 2019). "Additionally, Seimiya’s group observed that G4 binding to splicing factor 3B subunit 2 (SF3B2) downregulated STAT1 phosphorylation and interferon-stimulated gene (ISG) expression in 3D-cultured cancer cells." (PMID 40333779, 2025). "Another possibility is that EQ selectively downregulates level of SF3B2 in neuronal cells but not in cancer cells." (PMID 27350330, 2016).
tumor (4 papers, 2019 to 2023). "On the other hand, SF3B2 expression positively correlated with the neoplasm histologic grade (q = 5.636e−6) but not with HPV status (q = 0.145), alcohol consumption frequency (q = 0.322), or cigarette smoking history (q = 0.354)." (PMID 35715826, 2022). "High SF3B2 expression was also associated with poor overall survival in patients with HNSCC and promoted tumor growth in mouse HNSCC xenograft model." (PMID 35715826, 2022). "SF3B2 promotes tumor growth, owing to its involvement in activation of gene expression associated with mitochondrial electron transport and transcription regulatory region DNA binding." (PMID 35715826, 2022). "SF3B2 knockout abrogated the tumor promoting effect of RNF6 overexpression, whereas the reexpression of SF3B2 recused cell growth and migration/invasion in RNF6 knockout cells, indicating that SF3B2 is a functional downstream target of RNF6 in CRC." (PMID 34611311, 2021). "Taken together, these data suggest that tumor promoting function of RNF6 in CRC was dependent on the upregulation of SF3B2 expression." (PMID 34611311, 2021). "SF3B2 mRNA expression was upregulated in 64.9% (98/151) of primary CRC tissues compared to their adjacent non-tumor tissues (P < 0.0001)." (PMID 34611311, 2021). "Thus, SF3B2 has a distinct role in RNA splicing from the U2 snRNP complex, and its high expression contributes to tumor progression." (PMID 35715826, 2022). "Thus, further studies are required to fully understand how SF3B2 modulates both transcription and RNA splicing to promote tumor progression in patients with HNSCC." (PMID 35715826, 2022). "Conversely, SF3B2-depleted cells had decreased expression of genes related to transcription regulatory region DNA binding, suggesting that high SF3B2 expression promotes tumor cell proliferation by changing the gene expression profile." (PMID 35715826, 2022). "To evaluate whether RNF6 induces tumor progression through regulating SF3B2, we transfected SF3B2 knockout HCT116 and HT29 cells with RNF6 expression plasmid or empty vector." (PMID 34611311, 2021).
SF3B2 also shares sentences with these, for which no sentence is quoted: breast carcinoma (2 papers); acute myeloid leukemia (1); autism (1); Burn–McKeown syndrome (1); Cerebro-costo-mandibular syndrome (1); colorectal cancer (1); glioma (1); hearing loss (1); infection (1); lung adenocarcinoma (1); malignant pleural mesothelioma (1); mandibulofacial dysostosis (1); meningioma (1); microcephaly (1); microtia (1); Nonsyndromic Orofacial Cleft (1); pancreatic adenocarcinoma (1); papillary carcinoma (1); renal carcinoma (1); renal cell carcinoma (1); retinitis pigmentosa (1).